S100B (S100 calcium binding protein B)
Diseases named in the same sentence as S100B in open-access papers (continued):
Sharing a sentence is not in itself a finding about the gene and the disease.
inflammatory bowel disease (11 papers, 2011 to 2025). A spectrum of small and large bowel inflammatory diseases of unknown etiology. "Given that S100B is implicated in pathological conditions such as inflammatory bowel disease, post‐infectious irritable bowel syndrome, and other neuroinflammatory disorders, it emerges as a promising target for disease intervention." (PMID 40936303, 2025). "Converging evidence indicates a possible involvement of the S100B protein in the pathogenic processes of inflammatory bowel disease (IBD), a term indicating two conditions (Crohn’s disease and ulcerative colitis) that are characterized by chronic inflammation of the gastrointestinal tract." (PMID 37298554, 2023). "Although S100B is considered mainly as a biomarker in neuroinflammatory disorders, experimental evidence also suggests a role of S100B in inflammatory diseases of the gut, such as in inflammatory bowel disease." (PMID 39766257, 2024). "A loss of S100β+ glial cells or glial networks was linked previously to increased proinflammatory cytokine levels (e.g., IFN-γ and TNF-α) in patients with inflammatory bowel disease." (PMID 39207863, 2024). "Abnormalities in the enteroglial network were described in the intestinal mucosa of patients with inflammatory bowel diseases (IBD), measures as the reactive enteric gliosis, i.e. the massive over-expression and secretion of S100B protein, a cell-specific astroglial derived signalling molecule." (PMID 22163000, 2011). "In the small intestine of patients with Crohn’s disease, a type of inflammatory bowel disease (IBD), SOX10, PLP1, and S100B transcripts were highly enriched in mucosal glia while GFAP was enriched in various non-glial cells including fibroblasts and immune cells." (PMID 40227232, 2025).
lung carcinoma (11 papers, 2008 to 2025). "S100A4 and S100B overexpression is associated with poor prognosis and tumor metastasis in lung cancer (seeTable 2for roles in lung diseases)." (PMID 41164170, 2025). "However, contrary to our expectation, high expression of S100B in lung cancer was associated with better OS in this study." (PMID 29607329, 2018). "In a study looking at the presence of S100B in the serum of 38 patients with lung carcinoma, an elevated S100B level was either associated with brain metastases or with the presence of imaging changes suggestive of chronic, diffuse cerebral microvascular disease." (PMID 18798997, 2008). "For example, overexpression of S100B leads to enhanced migration and invasion of lung cancer cell lines, thereby promoting brain metastasis." (PMID 35785160, 2022). "The expression of S100P (HR = 1.4, 95% CI: 1.02–1.93, and p = 0.0340) and S100B (HR = 0.47, 95% CI: 0.24–0.93, and p = 0.025) was modestly associated with OS in patients with grade II and III lung cancer, respectively." (PMID 29607329, 2018). "Serum S100B and S100B autoantibodies are biomarkers of lung cancer brain metastasis." (PMID 35785160, 2022). "Therefore, the molecular mechanisms of S100B in lung cancer need to be further evaluated to classify this protein in a clinical context." (PMID 32722137, 2020). "S100B was introduced as a possible biomarker for brain metastasis in lung cancer patients." (PMID 32722137, 2020). "They tested the serum S100B protein concentration and MRI scans in 38 newly diagnosed lung cancer patients without neurological symptoms and without a known history of brain metastasis." (PMID 40361513, 2025). "In lung cancer, S100B levels were shown to be elevated in patients with nonsmall cell lung cancer (NSCLC) with brain metastases." (PMID 35368338, 2022). "To date, S100B has been proven to be a cancer-promoting factor, whose overexpression can promote the proliferation, invasion and metastasis of lung cancer cells, exhibiting significant negative correlation with the prognosis of patients." (PMID 36581948, 2022).
myocardial infarction (11 papers, 2010 to 2023). Gross necrosis of the myocardium, as a result of interruption of the blood supply to the area, as in coronary thrombosis. "S100B, predominantly expressed in the nervous system, has been associated with cardiovascular injury following myocardial infarction or norepinephrine stimulation." (PMID 38275751, 2023). "In summary, the level of novel homeostatic calmodulin in S100B is elevated in the early stages of myocardial infarction, and the S100B variant rs9722 is independently associated with AMI patients in the Han Chinese population." (PMID 33796567, 2020). "Increased S100B levels were associated with the acute coronary syndrome, and S100B expression was related to myocardial injury in rat models of myocardial infarction." (PMID 33796567, 2020). "Forced expression of S100B in neonatal rat myocyte cultures and high level expression of S100B in transgenic mice hearts inhibit cardiac hypertrophy and the associated phenotype but augments myocyte apoptosis following myocardial infarction." (PMID 20672023, 2010). "S100B can negatively regulate myocardial hypertrophy, promote cell apoptosis, and participate in ventricular remodeling after myocardial infarction." (PMID 37217870, 2023). "In contrast to extracellular S100A1, which inhibits cardiomyocyte apoptosis, S100B is released into plasma after myocardial infarction and regulates apoptosis through extracellular mechanisms." (PMID 37217870, 2023). "We have previously shown that S100B released by damaged myocytes post myocardial infarction binds to RAGE, and induces myocyte apoptosis." (PMID 38275751, 2023). "- Levels of neutrophil-derived S100B, a novel homeostatic calmodulin, are elevated in the early stages of myocardial infarction." (PMID 33796567, 2020). "By contrast, knocking out S100B, augments hypertrophy, decreases apoptosis and preserves cardiac function following myocardial infarction." (PMID 20672023, 2010). "S100B is induced in the myocardium of human subjects and an experimental rat model following myocardial infarction." (PMID 20672023, 2010). "There is increasing evidence with experimental rodent models that S100B may play a role in the adverse ventricular remodeling process after myocardial infarction, its production being induced as a response to α1-adrenergic stimulation." (PMID 34821692, 2021). "Also, by activating a transcriptionally inducible form of nitric oxide synthase (iNOS), S100B plays a role in modulating the apoptosis process of cardiomyocytes during myocardial infarction." (PMID 34821692, 2021). "Similarly, thirty five days after experimental myocardial infarction, the S100B knockout mice mounted an augmented hypertrophic response compared to wild-type mice." (PMID 20672023, 2010). "Taken together, our results suggested that S100B might play a crucial role in the occurrence of AMI, especially in the early stages of myocardial infarction." (PMID 33796567, 2020). "S100B not normally expressed in the myocardium, is induced in the peri-infarct region of the human heart after myocardial infarction and in rat heart commencing at day 7 following myocardial infarction as a result of experimental coronary artery ligation." (PMID 20672023, 2010).
neuroblastoma (11 papers, 2008 to 2025). Neuroblastoma (NB) is the most common solid, extracranial childhood tumor. "HOXC6 and HOXC11 have been shown to induce differentiation of GOTO neuroblastoma cells into Schwannian cells via transcription activation of S100β." (PMID 31379707, 2019). "Our data are in line with the function of S100B with trophic or toxic effects on neurons or neuroblastoma cells depending on its concentration via RAGE ligation." (PMID 21559403, 2011). "In fact, it has been reported that S100b protects LAN-5 neuroblastoma cells against beta-amyloid-induced neurotoxicity at lower nanomolar doses, while S100b was toxic to LAN-5 cells at micromolar doses." (PMID 20508809, 2010). "Similarly, RAGE-dependent apoptosis has been described also in neuroblastoma cells exposed to S100B or AGEs." (PMID 27313835, 2016). "Six experimental constructs (GLUL 500±UTR, RLBP1 500±UTR, and S100b 500±UTR) were tested by transfection in 3 cell types: wMC Muller cells, NIH/3T3 fibroblasts, and Neuro-2a neuroblastoma cells." (PMID 18437242, 2008). "Indeed, HMGB1 and the two S100 family proteins, S100B and S100A1, increase the expression of the antiapoptotic protein Bcl-2, in a RAGE-dependent way, favoring neuroblastoma cell survival." (PMID 27313835, 2016). "Here, neuroblastoma (NB) cell line subtypes were characterized according to embryonic peripheral nervous system development markers (GAP43, Phox2b, Sox10, c-kit, GD2, NF68, vimentin, S100β, calcyclin and ABCG2), morphological features, gene expression and differentiation potential." (PMID 19216736, 2009).
type 2 diabetes (11 papers, 2014 to 2025). "An exception to this pattern was a study of cognitive function in people with type 2 diabetes, which found that higher levels of S100B were associated with better cognitive function." (PMID 35585111, 2022). "In this study, we investigated the associations between the levels of NSE and S100B protein and coma duration, and evaluated the optimal cut-off values for prediction coma duration ≥ 72 hours in patients with ACOP." (PMID 34160445, 2021). "The serum level of S100B is directly correlated with hyperglycemia and hyperinsulinemia in streptozocin-induced type II diabetes as a model of IR." (PMID 37891752, 2023). "This study explored the correlation and predictive value of NSE and S100B protein on coma duration in patients with ACOP." (PMID 34160445, 2021). "The NSE and S100B protein levels were significantly correlated with the degree of impaired consciousness and had the same clinical value in predicting coma duration of ≥ 72 hours in patients with ACOP." (PMID 34160445, 2021). "After adjusting for confounding factors, serum S100B levels were positively correlated with cognitive function in type 2 diabetes patients." (PMID 32112645, 2020). "The purpose of this study was to investigate the correlation between serum S100B levels and cognitive function in type 2 diabetes patients." (PMID 32112645, 2020). "The AUC of NSE to predict coma duration ≥ 72 hours was 0.754 [95% confidence interval (95% CI): 0.603–0.870]; the AUC of S100B to predict coma duration ≥ 72 hours was 0.791 (95% CI: 0.644–0.898), and the AUC of GCS score to predict coma duration ≥ 72 hours was 0.785 (95% CI: 0.637–0.893)." (PMID 34160445, 2021). "The aim of this study was to investigate the associations between the levels of neuron-specific enolase (NSE) and S100B protein and coma duration, and evaluate the optimal cut-off values for prediction coma duration ≥ 72 hours in patients with acute carbon monoxide poisoning (ACOP)." (PMID 34160445, 2021). "The different roles of S100B in AD and type 2 diabetes may be related to disease progression and different disease stages." (PMID 32112645, 2020). "It is suggested that S100B may be involved in the occurrence and development of cognitive dysfunction in type 2 diabetes patients and play a protective role." (PMID 32112645, 2020). "In conclusion, the NSE and S100B protein levels were significantly correlated with the degree of impaired consciousness in patients with ACOP, and they had the same clinical value in predicting coma duration ≥ 72 hours." (PMID 34160445, 2021).
ulcerative colitis (11 papers, 2011 to 2025). An inflammatory bowel disease involving the mucosal surface of the large intestine and rectum. "Studies have demonstrated that S100B protein is directly involved in gut inflammatory disease such as Crohn’s disease and ulcerative colitis." (PMID 40618170, 2025). "In an RNA sequencing profile comparing colonic mesenchyme between healthy and ulcerative colitis mice, glial cells were typically clustered by the expression of their markers S100B and GFAP, and possible additional markers include Hapln1 and POSTN." (PMID 37551711, 2024). "For example, high GFAP and S100β expression is a feature of mucosal inflammation in patients with ulcerative colitis (UC) or Crohn’s disease (CD)." (PMID 37779161, 2023). "Others have found that S100B activity is likewise involved in a variety of inflammatory diseases, such as ulcerative colitis, celiac disease, and chemotherapeutic-induced intestinal inflammation." (PMID 34568098, 2021). "In several intestinal inflammatory diseases, such as Crohn’s disease, celiac disease, and ulcerative colitis in humans, enteric glia mediate NO-dependent inflammation through S100β overexpression and release." (PMID 34829900, 2021). "In the present study, we explored (a) the endogenous expression of glial S100B protein in human colonic mucosa from healthy, peritumoral, ulcerative colitis (UC) and cancer biopsies and its correlation with the expression of pro‐inflammatory markers and pro‐apoptotic factors." (PMID 32022398, 2020). "Ulcerative colitis patients had significantly lower serum S100B levels, while GFAP was of no diagnostic value in UC patients." (PMID 24790767, 2014). "Exogenous S100B (0.005‐5 μmol/L) alone, or in the presence of PENVE (0.005‐5 μmol/L), was tested in control biopsies while PENVE (5 μmol/L) was evaluated on control, peritumoral, ulcerative colitis and colon cancer biopsies." (PMID 32022398, 2020).
brain tumors (10 papers, 2015 to 2025). "We found S100B upregulated in the brain tumor group, consistently with its role as neuronal survival protein." (PMID 33469081, 2021). "Serum neuronal biomarkers, such as neuron-specific enolase (NSE), S100β, and glial fibrillary acidic protein (GFAP), have been reported to be upregulated in patients with brain tumors caused by brain injuries." (PMID 28969023, 2017). "However, it was not a prognostic biomarker of primary brain tumors, potentially because S100β is less specific to neurons and is distributed in several cell tissues." (PMID 28969023, 2017). "Yet, the absence of GFAP and S100β expression in the adult brain tumors is intriguing." (PMID 25644510, 2015). "Therefore, this study investigated the potential pretreatment prognostic value of serum neuronal and nonneuronal biomarkers, namely NSE, S100β, GFAP, NGAL, LDH, and lactate, in patients undergoing supratentorial primary brain tumor resection." (PMID 28969023, 2017).
fibromyalgia (10 papers, 2014 to 2025). A chronic disorder of unknown etiology characterized by pain, stiffness, and tenderness in the muscles of neck, shoulders, back, hips, arms, and legs. "In fibromyalgia patients, for example, it was found that increased serum concentrations of S100B were associated with a lower pressure-pain threshold." (PMID 32379790, 2020). "Although serum S100B may be elevated in acute neuronal damage, S100B levels were decreased in patients with underlying neurodegenerative disease and also observed in patients who carry lower pain thresholds diagnosed with fibromyalgia." (PMID 31824318, 2019). "HMGB1 and S100B expression was markedly increased in the lumbar SC of the fibromyalgia mice compared to that in the normal mice (Tukey’s test, * p < 0.05, n = 6)." (PMID 41008336, 2025). "Our results indicated that both HMGB1 and S100B were increased after fibromyalgia induction, and this was mitigated by EA (Tukey’s test, * p < 0.05, n = 6) but not by PD-L1 injection." (PMID 41008336, 2025). "Next, we determined whether HMGB1 and S100B were involved in this fibromyalgia model and the effects of EA or PD-L1." (PMID 41008336, 2025). "In addition, there were increased HMGB1 and S100B immuno-positive signals in the SSCs of the fibromyalgia mice compared to those in the normal mice (Tukey’s test, * p < 0.05, n = 6)." (PMID 41008336, 2025). "S100B is the most studied S100 protein in patients with this chronic condition, and it has been found to be significantly elevated in serum of women with several chronic pain conditions, including fibromyalgia." (PMID 38797848, 2024). "Further, levels of microglia/astrocytes and also HMGB1 and S100B were increased, whereas PD-1 was decreased, in the DRG, SC, thalamus, SSC, and CB5-7 of fibromyalgia mice." (PMID 41008336, 2025). "Finally, we showed that S100B and HMGB1 regulate TRPV1 and its signalling pathways and propose TRPV1 as a potential therapeutic target for fibromyalgia." (PMID 35341159, 2022). "The present study aimed to investigate whether EA reduces fibromyalgia pain by inhibiting the HMGB1, S100B, and TRPV1 signalling pathways in the mouse brain." (PMID 35341159, 2022).
cutaneous melanoma (9 papers, 2011 to 2025). A primary melanoma arising from atypical melanocytes in the skin. "Serum lactate dehydrogenase (LDH) and S100B protein levels are also associated with a poor prognosis and a diminished response to therapy in cutaneous melanoma patients." (PMID 36713580, 2022). "The use of S100B, in this manuscript abbreviated as S100, is common as a serum tumor marker for cutaneous melanoma and has been established for a long time." (PMID 36979464, 2023). "Increased level of serum S100B can serve as a marker of metastatic spread in patients with cutaneous melanoma (CM)." (PMID 21810220, 2011).
Hyperglycemia (8 papers, 2015 to 2025). An increased concentration of glucose in the blood. "S100B was investigated in two studies, with divergent findings: one showed a positive association with glycaemic status, while the other reported lower levels in hyperglycaemia." (PMID 41150802, 2025). "Additionally, the study revealed an association between chronic hyperglycaemia and cognitive function, reporting lower S100B levels in individuals with T2DM compared to healthy controls." (PMID 41150802, 2025). "Once extracellular, S100B functions both as a damage-associated molecular pattern and as a mediator of neuroinflammation, linking hyperglycaemia-driven oxidative stress to astrocytic activation and S100B secretion." (PMID 41296388, 2025). "The finding of higher S100B maternal blood levels, in relation with perinatal growth and hyperglycemia in GDM women, warrants further consideration." (PMID 35162052, 2022). "However, astrocyte markers, including CD44, KCNJ10, TGFBR2, GFAP, and S100β, were upregulated under hyperglycaemia, as shown by both NGS transcriptomic analysis and immunostaining." (PMID 41419458, 2025). "Additionally, the chronic hyperglycemia encountered during DKA can impair the neurotransmitter system and myelin production in a developing brain and S100B levels may accordingly be increased in DKA patients." (PMID 26316432, 2015).